TOP2A (DNA topoisomerase II alpha)
Diseases named in the same sentence as TOP2A in open-access papers (continued):
Sharing a sentence is not in itself a finding about the gene and the disease.
prostate carcinoma (continued). "In addition, TOP2A overexpression was also reported in other cancer types, such as prostate cancer, endometrial cancer, colorectal, and lung carcinomas, and so on." (PMID 28969025, 2017). "TOP2A is frequently overexpressed in aggressive prostate cancer (PCa)." (PMID 26560244, 2015). "Thus, TOP2A is a marker for secondary prostate cancer, and its overexpression correlates with high Gleason scores, metastasis and poor prognosis of prostate cancer." (PMID 25237769, 2014). "The results of our study reported here show that TOP2A is the phenotype of recurrence/metastasis in prostate cancer and a marker of rapid proliferation, whereas TOP2Aneg cells are CSCs and could regenerate TOP2Ahigh proliferative cells." (PMID 25237769, 2014). "It has been previously reported that TOP2A accumulation is induced by SPOP mutation and contributes to prostate cancer progression from the accumulation of DNA damage, and etoposide could be effective for SPOP mutation prostate cancer." (PMID 37240308, 2023). "Furthermore, we determined that RNA-mediated interactions between BAZ2A and TOP2A and KDM1A repress genes critical to PCa and may prove to be useful to stratify prostate cancer risk and treatment in patients." (PMID 37184661, 2023). "Finally, 5hmC sequencing of cell-free DNA from patients with metastatic disease proved useful as a prognostic biomarker able to identify an aggressive subtype of prostate cancer using the genes TOP2A and EZH2, previously only detectable by transcriptomic analysis of solid tumor biopsies." (PMID 36251389, 2022). "In addition, TOP2α is used as a proliferation marker in multiple cancer types, including CRC56,57, and elevated levels of TOP2α expression are associated with metastasis in prostate cancer, pancreatic cancer, and breast cancer." (PMID 32358485, 2020). "Therefore, TOP2A is also an excellent prognostic marker for prostate cancer." (PMID 25237769, 2014). "Therefore, we explored the relationship of TOP2A expression and CSCs in prostate cancer." (PMID 25237769, 2014). "However, little information is available about TOP2A expression in prostate carcinoma." (PMID 23398928, 2013). "The boxplot demonstrated that SLPI is down-regulated in prostate cancer patients, while the CENPF, TOP2A and OR51E2 are up-regulated in prostate cancer patients compared with the normal cohort." (PMID 36937411, 2023). "In preclinical prostate cancer mouse cell line models, the simultaneous elevation of Top2a and EZH2 results in hypersensitivity to combined treatment with etoposide, a Top2-targeting toxin, and inhibitors of EZH2." (PMID 36678591, 2023). "We have previously shown that the tissue gene expression levels of the genes TOP2A and EZH2 can identify an aggressive subgroup of prostate cancer." (PMID 36251389, 2022). "CKS2, TK1, MKI67, TOP2A, CCNB1 and RRM2 directly related to the recurrence and prognosis of prostate cancer." (PMID 32266115, 2020). "CDC25C, CDCA5, TOP2A, and CENPU, genes whose expression levels were strongly correlated to CENPA expression in prostate cancer tissue, were all notably down-regulated with CENPA depletion, as well as bound by CENPA." (PMID 32371391, 2020). "Furthermore, TOP2A expression has been reported to be a valuable prognostic marker for tumor advancements, recurrences, and predictor of poorer survival in small cell lung cancer, ovarian, colon, breast, and prostate cancers, as well as nasopharyngeal carcinoma." (PMID 25695068, 2015). "Therefore, we further investigated whether TOP2A was a potential CSC marker in prostate cancer." (PMID 25237769, 2014). "Similarly, overexpression of TOP2A was associated with advance histological grading, vascular invasion, and an early age onset of HCC, while CDKN3 was reported as part of a vascular invasion signature in HCC and has been implicated in other malignancies including breast and prostate cancers." (PMID 22539975, 2012).
prostate carcinoma (continued). "Given that neither TOP2A nor EZH2 commonly harbor somatic changes in prostate cancer that can be detected by DNA sequencing, this highlights the potential of 5hmC-seq to add to current analyses of cfDNA in advanced cancers." (PMID 36251389, 2022). "Neither gene is frequently altered by copy number changes in mCRPC; EZH2 had DNA alterations in 0.5% of 1465 samples, while TOP2A is not commonly included in prostate cancer targeted panels." (PMID 36251389, 2022). "UBE2C, PDZ-binding kinase (PBK), cyclin B1 (CCNB1), Cyclin-dependent kinase inhibitor 3 (CDKN3), topoisomerase II alpha (TOP2A), Aurora kinase A (AURKA) and MKI67 were identified as the candidate hub genes, which were all correlated with prostate cancer patient’ disease-free survival in TCGA." (PMID 33630978, 2021). "Overexpression of prostate cancer-associated SPOP mutants (e.g., Y87C, and F133V) increased the amount of TOP2A, but not TOP1, in the nuclei as well as the drastic accumulation of γH2AX in the nuclei." (PMID 33023230, 2020). "Furthermore, we confirmed that CSCs are enriched in TOP2A negative prostate cancer cells by directly sorting tumor cells based on their endogenous TOP2A expression followed by assessing sphere formation capability in vitro and sustained tumorigenesis in vivo." (PMID 25237769, 2014). "In conclusion, we believe that therapeutics targeting TOP2A negative cells, in combination with treatments to kill TOP2A positive cells, may provide a better method to eradicate primary prostate cancer." (PMID 25237769, 2014). "FISH probes for human TOP2A mRNA were confirmed to specifically stain human prostate cancer cells (PC3, LNCaP) and not stain mouse fibroblast or muscle cell lines (3T3, RAW 264.7) which do not express TOP2A." (PMID 29335461, 2018).
lung cancer (45 papers, 2012 to 2025). A malignant neoplasm involving the lung. "Previously, both SPAG5 and TOP2A were identified as hub genes associated with accelerated COVID-19 infection in lung cancer patients." (PMID 39596028, 2024). "This study also revealed several up-regulated genes associated with lung cancer such as TOP2A and MKI67, and with tumor metastasis such as CDH11 and CD44." (PMID 34492061, 2021). "Among these genes, only TOP2A exhibited significant overexpression in lung cancer tissues relative to normal lung tissues, and high levels of TOP2A were significantly linked to lower overall survival in lung cancer patients compared to those with low expression." (PMID 41301416, 2025). "Lung cancer-associated gene microarrays were obtained from GEO and TCGA datasets, and TOP2A significantly co-expressed genes (|R| > 0.6, p < 0.01) were obtained from three microarrays, TCGA-LUAD, GSE19804, GSE116959, and 1111, 1194 and 247 genes were obtained, respectively." (PMID 37407689, 2023). "In addition, the mutations of TOP2A are associated with chemotherapy resistance in lung cancer." (PMID 33308216, 2020). "This study demonstrated the high potential of abietic acid, a compound that targets TOP2A, in the discovery of drugs for treating lung cancer." (PMID 41301416, 2025). "Curiously, high levels of SatIII RNA in human lung cancer cells have also been suggested to provide etoposide resistance by sequestering TOP2A to nuclear stress bodies." (PMID 40855509, 2025). "Western blotting analyses revealed a notable decrease in the expression of TOP2A in lung cancer cells." (PMID 41301416, 2025). "Further results demonstrated that abietic acid induces DNA damage in lung cancer cells through targeting DNA topoisomerase II alpha (TOP2A)." (PMID 41301416, 2025). "The following protein analysis using Western blotting indicated that abietic acid inhibited the expression of TOP2A in lung cancer cells." (PMID 41301416, 2025). "Our research results indicate that abietic acid induces DNA damage in lung cancer cells by downregulating TOP2A." (PMID 41301416, 2025). "Recent results show that in response to heat stress, human satellite III RNA recruits topoisomerase IIa (TOP2A) to nuclear stress bodies and generates resistance against the TOP2A inhibitor etoposide in lung cancer." (PMID 35885937, 2022). "qRT-PCR confirmed that the expression level of CDKN3, MKI67, CEP55, SPAG5, AURKA, TOP2A were highly expressed in lung cancer tissues." (PMID 35178291, 2022). "Here we show that the long non-coding satellite III RNA (SatIII) generates resistance against the topoisomerase IIa (TOP2A) inhibitor etoposide in lung cancer." (PMID 34031359, 2021). "Meanwhile, at 8 weeks after PHMG exposure, lung cancer-related genes such as TOP2A and MKI67 and tumor metastasis-related genes such as CDH11 and CD44 were significantly upregulated." (PMID 33737587, 2021). "Among lung cancer genes, TOP2A is a nuclear enzyme critical for the regulation of DNA transcription, replication, and recombination." (PMID 33737587, 2021). "Functional classification analysis revealed that lung cancer-related genes, such as TOP2A and MKI67, and tumor metastasis-related genes, such as CDH11 and CD44, were significantly up-regulated after 8 weeks of PHMG exposure." (PMID 33737587, 2021). "In the subsequent research, TOP2A with large interaction relations among the critical target genes related to lung cancer obtained by screening would be screened for drug resistance, providing assistance for the development of its inhibitors." (PMID 34616430, 2021). "Then we identified that the expression level of TOP2A was upregulated in both surgically removed lung cancer tissues and lung cancer cell lines." (PMID 32201520, 2020). "The purpose of this study was to assess the predictive role of particular single nucleotide polymorphisms (SNPs) in the promoter regions of TOP2A and ERCC1 genes in non‐small cell lung cancer patients (NSCLC) treated with chemotherapy." (PMID 31797573, 2020).
lung cancer (continued). "To further investigate the possible impact of TOP2A expression on lung cancer, we analyzed the relationship between TOP2A expression and clinical characteristics of lung cancer patients in the Kaplan-Meier plotter databases." (PMID 31816603, 2019). "The further define the correlation between TOP2A expression and immune infiltrates in lung cancer, gene markers of tumor-infiltrating immune cells were also evaluated." (PMID 31816603, 2019). "Correlation of TOP2A mRNA expression and clinical prognosis in lung cancer for different clinicopathological factors." (PMID 31816603, 2019). "Further analysis confirmed that TOP2A expression was correlated with the prognosis of early-stage lung cancer patients and was negatively correlated with immune cell infiltration in NSCLC, especially of DCs." (PMID 31816603, 2019). "Further analysis revealed that TOP2A had prognostic significance in early-stage lung cancer patients, and its expression correlated with levels of immune cell infiltration, especially dendritic cells (DCs)." (PMID 31816603, 2019). "From these results, we hypothesize that TOP2A may serve as a key target for DNA damage induced by abietic acid in lung cancer." (PMID 41301416, 2025). "Doxorubicin, etoposide, and teniposide are clinical TOP2A inhibitors used to treat lung cancer." (PMID 41301416, 2025). "Moreover, the GEPIA analysis results indicated that TOP2A was the only gene with markedly elevated expression in lung cancer tissues relative to normal tissues." (PMID 41301416, 2025). "E-cadherin expression in patients with lung cancer was negatively correlated with TOP2A, but N-cadherin expression was positively correlated with TOP2A, indicating that TOP2A may facilitate EMT." (PMID 38806610, 2024). "Moreover, previous studies have reported the expression of TOP2A as being regulated in lung cancer and lung cancer cell lines." (PMID 37304067, 2023). "Additionally, other studies suggested that TOP2A induced proliferation and invasion of different tumors, such as lung cancer, PCa, and CRC." (PMID 34939898, 2021). "Besides, TOP2A can be a biomarker for diagnosis, treatment, and prognosis in lung cancer, colon cancer, and ovarian cancer." (PMID 34737790, 2021). "In addition, a previous study reported that CCNA2, CDC20, PBK, and TOP2A that interacted with CDK1 play vital roles in survival outcomes in human lung cancer." (PMID 32426332, 2020). "Lung cancer is characterized by its invasion hence we investigate whether TOP2A knockdown influences lung adenocarcinoma invasion and migration." (PMID 32201520, 2020). "The protein levels of TOP2A and UBE2C were low in normal lung tissues, while the levels of these genes were high in lung cancer tissues." (PMID 35178291, 2022). "It has been reported in previous literature that NEK2, TOP2A, PLK1, CA4, and AURKB can play oncogenic or tumor suppressing roles in the progression of lung cancer." (PMID 35646063, 2022). "The clinical significance of TOP2A and probable signaling pathways it involved in were further explored, and a positive correlation between TOP2A and TPX2 expression was found in lung cancer tissues." (PMID 31528121, 2019). "Similarly, in lung cancer, radioresistance-related signatures also predict patient outcomes and immune status, identifying TOP2A, CDH3, ASPM, CENPF, SLC2A1, and PRC1 as potential detection biomarkers for early lung cancer." (PMID 41041339, 2025). "Thus, we will further investigate the molecular mechanisms of TOP2A and ADH1B genes in lipid metabolism regulation and lung cancer progression in upcoming studies." (PMID 37985446, 2023). "It was found that TOP2A, CCNB1, CCNA2, CDK1, and TTK might be the critical target genes of lung cancer." (PMID 34616430, 2021). "DRZ depleted TOP2A also from fibrosarcoma-derived cells, but not from lung cancer-derived and human embryo-derived cells." (PMID 25406834, 2014). "TOP2A, CCNB1, CCNA2, CDK1, and TTK may be the key target genes of lung cancer." (PMID 34616430, 2021).
lung cancer (continued). "This combination of TOP2A and ADH1B gene diagnostics and clinical lipid panel investigations might be an effective intervention for early and accurate diagnosis, targeted therapy, and improved prognosis of LUAD, thus enhancing the current clinical management strategies of lung cancer." (PMID 37985446, 2023). "DRZ (100 μM, 24 h) reduced the level of TOP2A protein in fibrosarcoma-derived HT1080, but neither in lung cancer-derived NYH cells, nor in human embryonic cells HEK293." (PMID 25406834, 2014). "However, it is not known whether TOP2A and ADH1B can also affect lipid metabolism in lung cancer patients with different subtypes." (PMID 37985446, 2023). "In addition, DEX reduced in vitro TOP2A levels and the accumulation of DOX-induced DSB in fibrosarcoma-derived cells but not in lung cancer cells, thereby highlighting the inconsistency of DEX in interfering with the anticancer effects of DOX as was also observed in the current study." (PMID 37927589, 2023).
glioma (42 papers, 2013 to 2025). A benign or malignant brain and spinal cord tumor that arises from glial cells (astrocytes, oligodendrocytes, ependymal cells). "In sum, we clarified the underlying role of β-catenin and the oncogenic function of TOP2A in glioma." (PMID 35012441, 2022). "We observed that a high level of TOP2A expression was dramatically linked with inferior survival in glioma patients while silencing of TOP2A impaired glioma cell proliferation and aggressiveness." (PMID 35012441, 2022). "In the current report, we aim to study the potential role of TOP2A in glioma and the underlying molecular mechanism." (PMID 35012441, 2022). "We corroborated that TOP2A is noticeably upregulated and high TOP2A expression was dramatically associated with inferior prognosis in glioma patients." (PMID 35012441, 2022). "Several studies have demonstrated that increased TOP2A expression in glioma cells is strongly associated with tumor metastasis and reduced survival in patients with glioma and that TOP2A is a prominent Wnt pathway activator in glioma, boosting cell growth, motility, and penetration." (PMID 38806610, 2024). "In addition, the mechanisms underlying TOP2A overexpression in glioma samples also remain to be elucidated." (PMID 35012441, 2022). "Thus, the potential mediation of TOP2A expression could represent another pivotal mechanism underlying ORC6-driven glioma cell growth." (PMID 38971772, 2024). "By understanding the molecular mechanisms underlying the dysregulation of TOP2A in gliomas, researchers may identify potential strategies to modulate its activity or expression, leading to improved therapeutic outcomes for patients with this aggressive brain tumor." (PMID 37593751, 2023). "The CNOT7 was positively correlated with transcription factors TOP2A or HDAC2 in glioma patients’ samples, especially HDAC2 (Spearmen = 0.42, Pearson = 0.41, R2 = 0.17)." (PMID 38985240, 2025). "Combined with the analysis results of our study, it was found that the grade of glioma was significantly correlated with TOP2A expression." (PMID 41284119, 2025). "In this study, we downloaded the gene expression data and clinical data of glioma in TCGA to analyze the direct relationship between TOP2A expression and patient survival prognosis and the correlation with patient clinical information." (PMID 41284119, 2025). "Topoisomerase II alpha (TOP2A), which is silenced by microRNAs such as miR-139 and miR-548c-3p, plays a critical role in glioma cell proliferation and migration." (PMID 41471245, 2025). "In our study, high-grade glioma tissues were observed to express high levels of TOP2A by immunohistochemical staining methods compared to low-grade glioma tissues." (PMID 41284119, 2025). "After undergoing bioinformatics analysis, in this study, we further explore the correlation between TOP2A and the clinical samples of real-world glioma patients, so as to analyze the relationship between TOP2A expression and the survival prognosis of patients." (PMID 41284119, 2025). "Through the biological function analysis of GSEA, genes with strong correlation with TOP2A and abnormally expressed to a certain extent in gliomas can be found." (PMID 41284119, 2025). "In previous studies, we analyzed the gene expression profile of glioma in TCGA database and found that the expression of TOP2A was positively correlated with the staging of glioma." (PMID 41284119, 2025). "The upregulation of TOP2A (DNA Topoisomerase II Alpha) is also a prognostic biomarker in patients with glioma." (PMID 40507925, 2025). "In this study, we retrieved 161 glioma tissue specimens from the pathology center of the First Affiliated Hospital of Anhui Medical University to further explore the expression of TOP2A in glioma staging." (PMID 41284119, 2025). "Representative IHCs are expressed at TOP2A staining intensity in gliomas, and images taken by Olympus SC180 microscopy distinguish immunohistochemistry between high-expression and low-expression groups." (PMID 41284119, 2025).